MC1R (melanocortin 1 receptor)
Diseases named in the same sentence as MC1R in open-access papers (continued):
Sharing a sentence is not in itself a finding about the gene and the disease.
melanoma (continued). "Then, we compared the expression of MC1R with that of other commonly expressed melanoma markers." (PMID 12177778, 2002). "MC1R is therefore expressed in a proportion of melanomas comparable to that of the melanocytic glycoprotein gp100, a protein which has proven a promising target as a melanoma vaccine." (PMID 12177778, 2002). "Conversely, two of the HBM45 negative melanomas expressed MC1R, including the depigmented variant DFW of the DFB line and the BL line, while one lacked the expression of both these markers (DL) while still staining positive for the S-100 mAb." (PMID 12177778, 2002). "Three different DC lines cultured for 7–9 days in medium containing GM-CSF and IL-4 (CD14−, CD36+ and CD83−) showed higher levels of intracellular MC1R than short time cultured monocytes, comparable to that observed in the low MC1R expressing BL melanoma cell line." (PMID 12177778, 2002). "The genetic landscape of melanoma includes rare high-penetrance genes, such as CDKN2A, which are implicated in some familial cases, as well as more common pigmentation-related genes, such as MC1R, that increase the susceptibility of fair-skinned individuals to melanoma." (PMID 39941357, 2025). "Furthermore, individuals possessing R alleles of the MC1R exhibit a 28% increased risk of developing melanoma, independent of other phenotypic factors." (PMID 40558591, 2025). "In addition, interactive effects of MC1R and OCA2 on melanoma risk were reported." (PMID 39682251, 2024). "Finally, our results also suggested that MC1R may be involved in the development of multiple cancers other than melanoma and plays relevant protective roles in a tissue-specific manner." (PMID 37679505, 2023). "“R” variants include D84E, R142H, R151C, R160W, and D294H and people carrying these variants MC1R have the highest risk of developing melanoma and non-melanoma skin cancers whereas “r” variants: V60L, V92M, and R163Q showed a weaker association with the RHC phenotype." (PMID 37608347, 2023). "Our data suggest that MC1R might be a valuable drug target in aggressive melanoma." (PMID 37790306, 2023). "Mc1R is highly polymorphic in northern European populations, with loss-of-function variants associated with red hair and fair skin, poor tanning ability, and an increased risk for melanoma, but Mc1R shows almost no functionally significant variation among African populations." (PMID 36731029, 2023). "In addition, we identified Mc1r as a candidate gene mediating immune evasion in B16F10 melanoma." (PMID 37714844, 2023). "Consequently, MC1-R seems to be a useful target for selective melanoma imaging and therapy." (PMID 37765089, 2023). "Thus, GNAS activation was sufficient to restore immune evasion of MC1R-depleted B16F10 melanoma." (PMID 37714844, 2023). "Given the anti-proliferative function of MC1R in melanocytes, its role in DNA repair, and its widespread expression in several cell types, we hypothesized that MC1R would have a protective effect on the pathogenesis of non-melanoma cancers." (PMID 37679505, 2023). "Increased genetic risk for melanoma can occur in the context of germline pathogenic variants in high-penetrance genes, such as CDKN2A and CDK4, risk variants in low- to moderate-penetrance genes (MC1R and MITF), and possibly due to variants in emerging genes, such as ACD, TERF2IP, and TERT." (PMID 37958811, 2023). "Moreover, MC1R’s unique expression on the surface of melanoma cells may open up promising opportunities for development of targeted therapeutics including antibody-drug conjugates (ADCs) or cell therapies such as CAR-T therapies." (PMID 37790306, 2023). "Several MC1R variants, such as R151C and D294H, are common in individuals of Caucasian descent and are associated with the so-called RHC phenotype characterized by light skin, blond or red hair, poor tanning ability, propensity to sunburn, and increased melanoma risk." (PMID 37762683, 2023).
melanoma (continued). "Therefore, controlling pigment formation by regulating MC1R may be an effective target for the prevention and treatment of melanoma." (PMID 36551302, 2022). "Interestingly, MC1R variants may substantially increase the penetrance of CDKN2A mutations and the risk of melanoma in affected families, particularly multiple MC1R variants and red hair color variants." (PMID 35465855, 2022). "Because many risk factors for melanoma also increase the risk for NMSC, such as family history, skin type, and sun exposure, carriage of one or more MC1R “R” variants likely confers a higher risk for melanoma among patients with NMSC compared to those who are noncarriers." (PMID 35959144, 2022). "Likewise, carriers of melanocortin 1 receptor (MC1R) variants presenting a shift in melanin synthesis from eumelanin to pheomelanin and consequent elevation of reactive oxygen species are at increased melanoma risk, independent of their sun exposure." (PMID 35740018, 2022). "These unexpected findings warrant further investigation to better understand factors mediating these intervention effects, in particular to guard against the incorrect perception that receipt of MC1R average-risk information translates to no risk of developing melanoma." (PMID 34201795, 2021). "This seems to confirm that MC1R gene may play a role in the pathogenesis of melanoma not only through the synthesis of melanin associated with the sun exposure, but also through a direct effect on melanocyte cellular transformation." (PMID 34442055, 2021). "Moreover, the number of MC1R variants also correlated positively with increased risk of melanoma development among individuals not showing the RHC phenotype." (PMID 34356109, 2021). "MC1R variants affect melanoma risk independent of phenotype." (PMID 34001865, 2021). "Currently, approximately 100 MC1R SNPs have been found in melanoma, although the significance of most SNPs is not clear, and approximately 10 of these SNPs have been shown to be important for the occurrence and development of melanoma and can be used for its diagnosis." (PMID 34698109, 2021). "Interestingly, epigenetic regulation of MC1R expression in melanoma has been recently investigated." (PMID 34356109, 2021). "The MC1R gene is considered a master regulator of pigment production and distribution throughout the skin (pigmentary function) as well as a regulator of antioxidant defenses and DNA repair mechanisms (non-pigmentary function), thereby supporting its role in melanoma development." (PMID 33748184, 2020). "In addition, pheomelanin pigment may induces oxidative stress, lipid damage, and consequent melanoma induction in murine model with BRAFV600E mutation and melanocortin 1 receptor (MC1R) inactivation in melanocytes (to mimic red skin phenotype)." (PMID 33091721, 2020). "Furthermore, hereditary melanoma has been associated with germline mutations in high-risk melanoma susceptibility genes (CDKN2A, CDK4, TERT, POT1), polymorphisms in intermediate-risk melanoma susceptibility genes (BAP1, ACD, TERF2IP, MC1R and MITF), and germline missense substitutions in MITF." (PMID 32276436, 2020). "Therefore, we can see Mc1r appears to play a receptor potentiating melanoma cell migration." (PMID 32117457, 2020). "The study indicated that MC1R variants are defective in association with PTEN following UV exposure, consequently failing to suppress the PI3K/AKT signaling pathway, and the MC1R deficiency-induced elevation in PI3K/AKT signaling drives oncogenic transformation in melanoma." (PMID 32714859, 2020). "Similarly, an upregulation of MC1R increases B16F10 melanoma motility." (PMID 28761621, 2017). "MC1R is highly polymorphic and several polymorphisms are non-functional or partially-functional; they have been associated with pigment phenotype and skin cancers in many recent studies, and play an important role in an individual’s melanoma risk." (PMID 29340229, 2017).
melanoma (continued). "Whether patients with CMN with germline MC1R variants are at an increased risk of melanoma development is not yet known." (PMID 28078671, 2017). "MC1R also mediates anti-inflammatory properties as well and may promote anti-melanoma immunity." (PMID 28871274, 2017). "MC1R variants may be involved in melanoma development, but melanomas are not dependent on the classical RHC phenotype." (PMID 29340229, 2017). "Several studies have previously shown the presence of variants within the MC1R locus that may have effects on melanoma risk independent of their effect on pigmentation." (PMID 28973033, 2017). "Because MC1R-mediated UV protection and melanoma resistance is proportional to the robustness of the cAMP response downstream of MC1R signaling and a variety of pharmacologic strategies exist to impact cAMP, it might be possible to exploit MC1R signaling as a UV- and melanoma-preventive strategy." (PMID 27303435, 2016). "Although there is clearly a need for much more investigation into the mechanisms, feasibility and consequences of pharmacologic MC1R targeting, the melanocortin-MC1R signaling axis may prove to be a useful target for rational development of novel UV-resistance and melanoma-preventive strategies." (PMID 27303435, 2016). "There are several previous reports of MC1R variation in association with anatomical site of melanoma, but they generally grouped sites together on the basis of sun-exposure before analyses and/or categorized MC1R variants differently, and are not directly comparable to this study." (PMID 25790105, 2015). "Similarly, we did not observe an association between variation in MC1R and TILs, which were shown to be an important independent prognostic feature of melanoma in GEM." (PMID 25790105, 2015). "The mechanisms through which MC1R variants associated with red hair and fair skin predispose to melanoma were not understood until recently, when it was shown that wild-type but not variant MC1R protein associates with PTEN and protects it from degradation after UVB exposure." (PMID 24743024, 2014). "Finally, patients with MC1R variants had a 5- to 15-fold increased risk of BRAF-mutant melanomas regardless of signs of chronic solar damage." (PMID 24416617, 2013). "Strikingly, α-MSH did not up-regulate the expression of cytotoxic genes in CD8+ T cells from melanoma patients with skin type 1 compared to PBS treated cells from the same patient suggesting that the induction of cytotoxicity in human CD8+ T cells requires functional MC-1R signaling." (PMID 20126537, 2010). "Recently, MC1R variants have been strongly associated with BRAF mutations in non-CSD melanoma, which has lead to the hypothesis that BRAF activation may be somehow indirectly induced by UV radiation." (PMID 19828018, 2009). "Furthermore, loss of MC1R function is associated with an increased incidence of melanoma and non-melanoma skin cancer." (PMID 19017395, 2008). "RNA coding for MC1R could also be detected in melanoma cells and in normal melanocytes." (PMID 12177778, 2002). "The Melanocortin-1 receptor (MC1R) is an attractive G protein-coupled receptor (GPCR) for melanoma targeting because of its high expression on both human and mouse melanoma samples." (PMID 40430268, 2025). "Melanocortin receptor 1 (MC1R), a GPCR highly expressed by melanomas, has also been investigated as a target for 212Pb TRT." (PMID 40591218, 2025). "zDHHC13 phosphorylation by AMPK at Ser208 enhanced MC1R S‐acylation, inhibiting UVB‐induced transformation of human melanocytes in vitro and delaying melanoma development in mice." (PMID 39429488, 2024). "Melanocortin-1-receptor (MC1R) is a cell surface receptor responsible for melanogenesis and it is overexpressed on the surface of melanoma cells, providing a good target." (PMID 38256168, 2024). "Both the melanocortin-1 receptor (MC1R) and the αvβ3 integrin receptor are attractive molecular targets for melanoma due to their over-expressions on melanoma cells." (PMID 38708130, 2024).
melanoma (continued). "Taken together, these data suggest that 50 EtOH and 95 EtOH can alleviate melanogenesis in human melanoma cells with inhibitory effects against MITF, TYR, TRP-1, and MC1R mRNA expression." (PMID 39335872, 2024). "Taken together, we conclude that MC1R represses the expression of Cxcl9, Cxcl10, and Cxcl11 in B16F10 melanoma." (PMID 37714844, 2023). "Our approach involved the permanent and complete knockout of endogenous MC1R in HBL cells, a human melanoma cell line of the triple WT molecular subtype, followed by stable transfection with WT, R151C or D294H constructs." (PMID 37762683, 2023). "Melanocortin-1 receptor (MC1R) is a G protein-coupled receptor that expresses at elevated levels in human melanotic and amelanotic melanoma." (PMID 37345092, 2023). "We evaluated the expression of melanocortin 1 receptor (MC1R) in two distinct cohorts of patients, namely those with primary (stage I-III) melanoma and those with distant metastasis." (PMID 37790306, 2023). "We found some evidence of GxE interactions with sun exposure, notably, with MC1R, CAT and NOS1 genes in melanoma, HAL and IL23A in BCC and HAL and XRCC1 in SCC." (PMID 37537768, 2023). "The melanocortin 1 receptor (MC1R), a G-protein-coupled receptor (GPCR), primarily located at the surface of melanocytes and melanoma cells, plays a crucial role in regulating the wide range of pigmentation degrees in mammals." (PMID 37048170, 2023). "Overall, these data demonstrated that the WT, R151C, and D294H forms of the MC1R were adequately and comparably expressed and processed in HBL human melanoma cells." (PMID 37762683, 2023). "Most notably, with MC1R, CAT and NOS1 genes in melanoma, HAL and IL23A genes in BCC and HAL and XRCC1 genes in SCC." (PMID 37537768, 2023). "Moreover, modulation of MC1R downstream signaling is likely to depend on the mutational landscape of melanoma cells, and melanocyte-specific responses such as regulation of MITF levels cannot be properly analyzed in heterologous cells engineered to express specific MC1R forms." (PMID 37762683, 2023). "NDPMSH-αPD-L1 maintains binding affinity to both melanocortin-1 receptor (MC1R) and PD-L1 on EK293-MC1R (melanoma) cells and showed thermal stability, serum stability and pharmacokinetic properties similar to the parental anti-PD-L1 mAb." (PMID 36052121, 2022). "Melanogenesis inhibition by SCE was assessed in vitro with B16-F10 melanoma cell models and in silico against melanin regulatory proteins Tyrosinase (TYR) and Melanocortin 1 Receptor (MC1R)." (PMID 36500679, 2022). "MC1R genetic testing and feedback may have utility in raising melanoma and nonmelanoma skin cancer risk awareness and improving communication between patients, family, and physicians about skin cancer risk, ultimately prompting screening and protective behaviors." (PMID 35959144, 2022). "Since both the RHC mutations of MC1R and the MGRN1–MC1R interaction decrease MC1R-dependent activation of the cAMP pathway, we hypothesized that the level of expression and/or the activity of MGRN1 may still have poorly characterized effects on key properties of melanocytes and melanoma cells." (PMID 35892921, 2022). "In contrast, non-CSD melanomas arise in younger individuals (age < 55) in intermittently sun exposed areas of the body, such as the trunk and proximal extremities; and arise more frequently in very fair individuals harbouring germline variants in MC1R (the red hair gene)." (PMID 35884596, 2022). "Of the eight GPCRs shown to be involved in pigmentation, only three have been studied in the context of melanoma (EDNRB, MC1R, and GRM1)." (PMID 35158973, 2022). "It is assumed that the increased level of cAMP triggered by MC1R activation is followed by induction of ERK in a cell-type seemed to be mediated by B-RAF, such as melanoma cells." (PMID 35889231, 2022).
melanoma (continued). "As the interaction of α-MSH with MC1R initiated the melanogenic signaling pathway through the cAMP–CREB–MITF axis, cAMP levels were measured in B16F10 melanoma cells." (PMID 34361022, 2021). "Another example is the use of MC1SP peptide, a ligand specific for melanocortin receptor-1 (MC1R), in the composition of polyplexes based on PEI–PEG to target murine melanoma tumor tissue." (PMID 34502287, 2021). "The evaluation of this compound was performed in vitro on MC1R-exhibiting B16F1 cells and in vivo in B16F1 melanoma-bearing mice." (PMID 34200477, 2021). "The MC1R/cAMP/MITF pathway is a key determinant for growth, differentiation, and survival of melanocytes and melanoma." (PMID 32605315, 2020). "After binding to MC1R, MTII elicits PTEN reactivation and AKT repression, thereby inhibiting the downstream NFκB/COX-2/PGE2 signaling to result in melanoma suppression." (PMID 31968661, 2020). "Linear and cyclic analogues of the α-melanocyte stimulating hormone (α-MSH) targeting the human melanocortin receptor 1 (MC1R) are of pharmacological interest for detecting and treating melanoma." (PMID 28714883, 2017). "The idea that loss of function of MC1R contributes to oncogenic transformation of melanocytes is supported by animal models based on the finding of a cooperation between null MC1R and BRAFV600E to promote melanoma development." (PMID 29156643, 2017). "We employed B16-F10 cell line, a human melanoma cell line (Mel 13) and two primary cultures of human melanocytes (NHM 1 and NHM 2, respectively), all expressing a wild type MC1R and responding to the αMSH in terms of pigmentation." (PMID 29020973, 2017). "Collectively these results provide compelling evidence for the significance of the MC1R and its signaling pathway in modulating the response of melanocytes to UVR, which is expected to maintain genomic stability and prevent melanoma formation." (PMID 27582758, 2016). "Consistent with inhibition of MC1R signaling, treatment with ASIP leads to a decrease in proliferation in a mouse melanoma cell line and an increase in melanocyte migration." (PMID 27303435, 2016). "Furthermore, MC1R variants are a modifying factor for melanoma risk in CDKN2A mutation carriers, suggesting that multiple medium- and low-penetrance genes may influence the risk conferred by high penetrance melanoma genes." (PMID 24742402, 2014). "In addition, to date there is no conclusion on the role of rare MC1R variants in melanoma." (PMID 24982914, 2014). "However due to the limited size of the present study we could not exclude a possible epistatic interaction of MC1R variants and 9p21 locus variants on melanoma risk." (PMID 23816148, 2013). "We show that multiple targets of Sox10 including Mc1r, the key signaling factor in skin and hair pigmentation, are involved as effectors in B16F10 melanoma cell migration." (PMID 22363655, 2012). "The melanocortin 1 receptor (receptor MC1R) is expressed predominately in melanocytes and melanomas." (PMID 22649681, 2011). "Western immunoblotting using the same primary anti-MC-1R antibody revealed a reactive band at 35 kDa molecular mass for the HBL, A375-SM and C8161 melanoma cell lines; close to the predicted size of MC-1R, based on sequencing information." (PMID 14612916, 2003). "Stable transfection of the C8161 cell line with the wild-type MC-1R and introduction of sensitivity to α-MSH provides possibly the strongest evidence yet that this receptor is involved in melanoma invasiveness." (PMID 14612916, 2003). "We also confirmed the presence of MC1R in activated monocytes/macrophages and in the THP-1 cell line, but at lower levels than those found in melanomas." (PMID 12177778, 2002). "However, although more studies are required to reveal the role of MC1R in the regulation of the immune response, this extensive analysis of MC1R tissue distribution may be of relevance not only for melanoma immunology but also dermatology, inflammation, and neuroimmunology." (PMID 12177778, 2002).